SNHG12 (small nucleolar RNA host gene 12)
Diseases named in the same sentence as SNHG12 in open-access papers (continued):
Sharing a sentence is not in itself a finding about the gene and the disease.
tumor (continued). "Taken together, above data suggested that expression of SNHG12 is significantly elevated in ccRCC tumour tissues, and high expression of SNHG12 is positively correlated with poor survival of ccRCC patients." (PMID 33787057, 2021). "Upregulation of SNHG12 predicted an advanced stage of tumour while knockdown of SNHG12 hampered tumour progression and stimulated apoptosis." (PMID 33968736, 2021). "In the present study, we for the first time elucidated that SNHG12 interacts with miR‐30a‐3p, a putative tumour suppressor, and antagonizes its tumour suppressive feature." (PMID 33787057, 2021). "Survival curves of the tumor samples indicate that SNHG12 is a carcinogenic factor; the higher the expression in the tumor, the worse the prognosis is (P = 0.0012, HR = 1.1)." (PMID 34372942, 2021). "The lncRNA SNHG12 (small nucleolar RNA host gene 12) has been shown to play a key role in tumor initiation and progression in different organs through a variety of mechanisms." (PMID 33593347, 2021). "For in vivo experiments, an intracranial xenograft tumor mouse model was used to investigate SNHG12 function." (PMID 32039732, 2020). "For instance, it was reported that SNHG12 mediated tumor immune escape through its involvement in unfolded protein responses." (PMID 33294456, 2020). "Zhou et al86 discovered that overexpression of SNHG12 was positively related to tumor grade, Enneking stage, tumor size, and metastasis as well as poor overall survival." (PMID 32249459, 2020). "Strikingly, SNHG12 knockdown in SKOV3 cells restored the effect of T cells treatment on controlling tumor size (p < 0.05)." (PMID 32927431, 2020). "Latest studies show the SNHG12 up-regulation, and the inhibition of tumor suppressor miRNAs, in many cancer types." (PMID 32318335, 2020). "The proliferation, metastasis and invasion of tumor cells are significantly proportional to the expression levels of SNHG12." (PMID 32432698, 2020). "We next explored the mechanisms underlying the high expression of SNHG12 in TMZ-resistant cells and tumor tissues after TMZ treatment." (PMID 32039732, 2020). "Further, SNHG12 up-regulation was positively correlated with advanced tumor stage and size, while it negatively correlated with patient survival, thus demonstrating its clinical significance." (PMID 31620362, 2019). "The predominant role of miR-199a-5p involving in the oncogenic signaling of SNHG12 was consolidated by introducing miR-199a-5p-specific inhibitor, wherein the anti-tumor effect elicited by SNHG12-knockdown was completely abrogated." (PMID 31114448, 2019). "SNHG12 up-regulation was positively correlated with advanced tumor stage and size, while it negatively correlated with patient survival." (PMID 31620362, 2019). "The altered expression of SNHG12 has been correlated with the viability, proliferation, metastasis, and invasion of tumor cells, impacting the prognosis and survival of cancer patients." (PMID 31620362, 2019). "SNHG12 up-regulation was positively correlated with tumor size, vascular invasion, and tumor node metastasis (TNM) stage, while it was negatively correlated with patient survival, demonstrating its clinical significance." (PMID 31620362, 2019). "Subsequently, they determined that SNHG12 is significantly up‐regulated in 102 TNBC tumour tissues compared to 95 non‐cancerous breast tissues by qRT‐PCR (P < 0.001)." (PMID 28941134, 2018). "Patients with higher SNHG12 expression levels were inclined to have larger tumours and metastatic lymph nodes." (PMID 28941134, 2018). "Our results showed that the expression of SNHG12 in HCC tissues was significantly higher than that in adjacent normal tissues and it was remarkably associated with tumor size (P < 0.05), vascular invasion (P < 0.05), and TNM stage (P < 0.05)." (PMID 28073380, 2017). "High expression of SNHG12 in CRC patients was significantly correlated with advanced tumor stage and large tumor size." (PMID 28225893, 2017).
tumor (continued). "High expression of SNHG12 in CRC patients was significantly correlated with advanced tumor stage (P=0.007) and large tumor size (P=0.004)." (PMID 28225893, 2017). "SNHG12 knockdown or cisplatin treatment led to a significant decrease in tumor volume and weight when compared with the control groups, and combination of SNHG12 knockdown and cisplatin treatment resulted in lower tumor volume and weight." (PMID 29137407, 2017). "Moreover, results of the present study revealed that SNHG12 knockdown markedly suppressed tumor growth and the metastasis of NSCLC." (PMID 40417819, 2025). "In addition, SNHG12-mediated upregulation of SCL7A11 suppressed tumor cell ferroptosis, and promoted the TAM2 polarization, proliferation, migration and invasion of NSCLC cells via sponging miR-326." (PMID 40417819, 2025). "Notably, SNHG12 knockdown suppressed NSCLC tumor growth and metastasis both in vivo and in vitro, highlighting the potential of SNHG12 as a therapeutic target in NSCLC." (PMID 40417819, 2025). "Meanwhile, SNHG12 knockdown in exosomes could significantly reduce the level of SNHG12 in tumor tissues." (PMID 38833118, 2024). "Overexpressed SNHG12 in LUAD promoted tumor proliferation and metastasis." (PMID 35726651, 2023). "Moreover, SNHG12 acts as a molecular sponge of microRNA to promote tumor proliferation, metastasis, and epithelial-mesenchymal transition." (PMID 37012358, 2023). "At the same time, RCC1/SNHG3/SNHG12 may in turn influence the regulation of immune cell infiltration in this tumor by directly or indirectly regulating the proliferation and differentiation of some immune cells." (PMID 36148010, 2022). "Furthermore, overexpression of SNHG3 and SNHG12 significantly promoted tumor proliferation, migration and invasion, suggesting that they are an oncogenic lncRNA." (PMID 36148010, 2022). "Moreover, SNHG12 is involved in unfolded protein responses, which many tumor cells use to evade immune-mediated attacks and enhance the polarization of effector immune cells." (PMID 35524329, 2022). "Furthermore, lncRNAs, including SNHG12, PACERR and HITT, function as key regulators of tumor-associated macrophages, regulating tumor cell proliferation, invasion and migration by altering the number of M2-polarized cells and contributing to immune escape." (PMID 36601121, 2022). "In addition, the high expression of SNHG12 was related to the tumor grade and poor prognosis of RCC patients, and the expression of SNHG12 in the tissues of informed RCC patients was related to tumor grade, TNM staging, and lymph node metastasis." (PMID 35597996, 2022). "Additionally, SNHG12, E2F7, p/t-MEK, and p/t-ERK expression pattern in tissues was reduced prominently whereas miR-129-5p expression pattern was increased when tumor-bearing mice were treated with EVs-sh-SNHG12 in comparison to EVs-sh-NC." (PMID 35383161, 2022). "Further bioinformatic analysis and molecular assays indicated that SNHG12 may have oncogenic activity in PC through sponging of miR-195, which is purported to act in a tumour-suppressive manner." (PMID 35159022, 2022). "This also indicates tumor- and subtype-specific expression of SNHG12." (PMID 36386805, 2022). "Also, there have been many reports indicating that SNHG3 and SNHG12 are aberrantly expressed in many tumor tissues and can be involved in the development of a variety of tumors and diseases." (PMID 36148010, 2022). "In addition, SNHG12 knockdown reverses RCC tumor resistance to sunitinib treatment and SNHG12 induces tumor growth in mouse models." (PMID 33593347, 2021). "In addition, the expression level of SNHG12 in GC samples was significantly related to tumor invasion depth, TNM stage and lymph node metastasis and was associated with disease-free survival (DFS) and overall survival (OS) in GC patients." (PMID 33994849, 2021). "Therefore, SNHG12 can be used as an effective biomarker to predict the prognosis and tumor progression of cancer patients." (PMID 34372942, 2021).
tumor (continued). "The current analysis shows that, whether in the TCGA database or in published articles, overexpression of SNHG12 is closely related to the poor prognosis of tumor patients." (PMID 34372942, 2021). "In a study, SNHG12 was markedly increased in PCa specimens, energizing tumour cells." (PMID 33968736, 2021). "Our data showed that expression of SNHG12 is significantly up‐regulated in ccRCC tumour samples." (PMID 33787057, 2021). "Moreover, in the sh SNHG12 group, both the volume and weight of tumours from mice fed sunitinib were obviously decreased, which revealed that low SNHG12 expression increased RCC sensitivity to sunitinib." (PMID 32641718, 2020). "Nevertheless, no apparent association was found between overexpression of SNHG12 and age (P = 0.403), gender (P = 0.291), tumor number (P = 0.586), and vascular invasion (P = 0.828)." (PMID 33294456, 2020). "Also, elevated SNHG12 expression was significantly correlated to larger tumor size, positive lymph nodes metastasis (LNM) and distant metastasis (DM), worse clinical stage, and drug resistance." (PMID 33124951, 2020). "From the results, we observed that knocking down SNHG12 inhibited tumour growth." (PMID 32641718, 2020). "Overall, we found that SNHG12 promoted tumour progression via CDCA3 in RCC cells." (PMID 32641718, 2020). "It is believed that SNHG12 could act as a molecular sponge of microRNAs to promote tumour proliferation, metastasis and epithelial-mesenchymal transition." (PMID 32641718, 2020). "Colony formation assays showed that miR-129-5p overexpression markedly suppressed TMZ resistance in SNHG12-depleted TMZ-resistant cells, while knockdown of miR-129-5p reversed SNHG12 knockdown-mediated suppression of tumor cell proliferation and chemoresistance." (PMID 32039732, 2020). "Furthermore, SNHG12 was found to promote IL-6/miR-21 crosstalk between tumor cells and M2 macrophages and facilitate cancer progression." (PMID 33294456, 2020). "SNHG12 has been reported to play an important role in MDR in tumor cells." (PMID 31620362, 2019). "In xenografted mice, knocking down SNHG12 reduced GC tumor growth." (PMID 31808752, 2019). "In addition, SNHG12 silencing inhibited migrative and invasive in vitro and xenograft tumor growth in vivo." (PMID 31114448, 2019). "MiR-199a-5p inhibition severely compromised SNHG12 silencing-elicited tumor repressive effects." (PMID 31114448, 2019). "We found that higher SNHG12 expression (P = 0.029), older age (P = 0.008), a greater tumor invasion depth (P = 0.030), lymph node metastasis (P = 0.001), distant metastasis (P = 0.007) and a higher TNM stage (P < 0.001) were associated with poorer survival in GC patients." (PMID 31808752, 2019). "These composite results support the conclusion that SNHG12 is up-regulated in NSCLC where it plays a direct role in the modulation of cancer progression through down-regulating the expression of tumor-suppressor miRNAs, such as miR-138 and miR-181a, and it is also involved in NSCLC drug resistance." (PMID 31620362, 2019). "SNHG12 knockdown inhibited tumor growth significantly after inoculation for 28 days." (PMID 28225893, 2017). "Therefore, SNHG12 may play a role in modifying the tumor microenvironment, leading to the increased growth of tumor cells and metastasis." (PMID 40417819, 2025). "In particular, several studies reported enhanced expression of SNHG12 in ccRCC tumors, which correlated with poor prognosis for patients, promoted viability, proliferation, migration and invasion, and inhibited apoptosis in vitro, as well as promoted ccRCC tumor growth in vivo." (PMID 34884928, 2021). "However, we did not encounter any association between SNHG12 expression and other clinical-pathological parameters such as age, gender, tumor location, tumor size, differentiation, lymph node metastasis, or TNM stage." (PMID 32943987, 2020).
tumor (continued). "Furthermore, in vivo experiments showed that SNHG12 increased tumour growth and that knocking down SNHG12 could reverse RCC sunitinib resistance." (PMID 32641718, 2020). "Thus, from this point of view, it is likely that inhibition of SNHG12 may also influence angiogenesis and depolarization of tumor-primed refractory immune cells contributing to immune restoration, though further studies are warranted." (PMID 31620362, 2019). "Thus, it adds to the list of tumor types in which SNHG12 may serve as an effective tool in the diagnosis and treatment of cancer." (PMID 31620362, 2019). "Exosome-derived SNHG12 promotes angiogenesis via the PBRM1/MMP10 axis, driving tumor growth, while SNHG9 inhibits the Hippo pathway through phosphatidic acid-induced LATS1 liquid–liquid phase separation, enhancing invasiveness." (PMID 41301542, 2025). "Using granulosa-like tumor (KGN) cells, we investigated glycolytic capacity and examined the relationship among SNHG12, PTEN and HMGB1 through RNA immunoprecipitation (RIP) and chromatin immunoprecipitation (ChIP) assays." (PMID 40486908, 2025). "In prostate cancer, SNHG6 modulates cancer cell sensitivity to paclitaxel by sponging miR-186, SNHG12 influences tumorigenesis through targeting miR-133b, and SNHG4 enhances ZIC5-mediated tumor growth and metastasis via the regulation of miR-377." (PMID 41301542, 2025). "Higher SNHG12 expression in RCC cell lines correlated with proliferation, migration and invasion of tumor cells." (PMID 38741178, 2024). "The expression levels of AC024060.2, LINC01138, AL034550.1, SNHG12, and AP001347.1 were upregulated in tumor tissues compared with those in the adjacent normal tissues." (PMID 35726651, 2023). "The expression of SNHG12 is positively correlated with the expression of MMP13, thus, MMP13 induced degradation of extracellular matrix in TNBC cells promotes tumor invasion and metastasis." (PMID 37795578, 2023). "Knockdown of SNHG12 blocked E2F1 recruitment and down-regulated the expression of CEP55, thereby inhibiting tumor formation and angiogenesis in nude mice." (PMID 35597996, 2022). "Compared with the NC, SNHG12 silencing slowed down tumor growth and reduced tumor weight, while further E2F1 overexpression boosted tumor growth and increased tumor weight." (PMID 35597996, 2022). "In particular, patients with NSCLC have been found to have enriched lncRNA SNHG12, which contributes to NSCLC cell growth, tumor metastasis, and drug resistance." (PMID 35658874, 2022). "In clear cell RCC, SNHG12, as a competitive endogenous RNA, competes with miR-30a-5p to bind to downstream oncogenes RUNX2, IGF-1R and WNT2 to promote tumor cell invasiveness." (PMID 35597996, 2022). "Small nucleolar RNA host gene 12 (SNHG12), located at the p35.3 region on chromosome 1, is a newly identified tumor-related lncRNA." (PMID 34239888, 2021). "Thus, SNHG12 could become a novel therapeutic target for anti-tumor therapy." (PMID 34195070, 2021). "Other oncogenic lncRNAs such as H19, HULC, SNHG12, and HOTAIR also demonstrated their regulatory functions in promoting cancer cell proliferation, inhibiting apoptosis, and aggravating tumor progression." (PMID 34456631, 2021). "After overexpression of SNHG12, the expression of SNHG12, the positive expression rate of HuR, and the mRNA level of FAM83B in tumor tissues were significantly increased." (PMID 34656115, 2021). "Six overlapping AS events regulated by SF3B4 in tumor samples were finally verified, including 1 SE event (ATP2B4) and 5 RI events in 4 genes (SRSF5, PHF6, SNHG12, KIAA1217)." (PMID 33563334, 2021). "SNHG3-203, TERC-201 and SNHG12-202 were upregulated, while ENST00000610809, ENST00000443132 and ENST00000619523 were downregulated in the EMPD tumor group." (PMID 34895219, 2021). "Our studies demonstrated the direct relationships among SNHG12, HuR and YWHAZ, which provides new evidence for improving tumor therapy and diagnosis." (PMID 34195070, 2021).
tumor (continued). "In this study, we show that SNHG12 binds to HuR to target ELAVL1 and YWHAZ, both of which are established tumor progression-related genes, and promotes GC cell proliferation via the YWHAZ/AKT/GSK-3β axis." (PMID 34195070, 2021). "Of note, a number of lncRNAs with broad oncogenic (SNHG12, CASC9, LUCAT1 and PVT1) or tumor suppressor (such as TINCR) function were also identified to be differentially expressed in cSCC25–28." (PMID 32108138, 2020). "In this study, we identified a new lncRNA small nucleolar RNA host gene 12 (SNHG12) and investigated its role in tumor immune escape." (PMID 32927431, 2020). "Studies have revealed that AATBC, ADAMTSL4-AS1, EPB41L4A-AS1, MIA-RAB4B, MIR4697HG, GAS5, SNHG12, MSX2P1, and LINC00852 are related to tumorigenesis and tumor progression in multiple cancers, such as bladder, breast, colorectal, and ovarian." (PMID 31850068, 2019). "In summary, our study found upregulated SNHG12 and downregulated miR-181a in NSCLC tumor tissues and cell lines." (PMID 29137407, 2017). "However, the decrease of SNHG12 expression in EVs reduced TAM2 polarization, weakened NSCLC cell proliferation, migration and invasion, and promoted tumor cell ferroptosis." (PMID 40417819, 2025). "Moreover, SNHG12-mediated upregulation of SLC7A11 suppressed ferroptosis and promoted the adaptation of NSCLC cells to TAM2 polarization in the tumor microenvironment." (PMID 40417819, 2025). "Similarly, all studied SNHGs are involved in EMT through activation of various athways including Notch-1, but in vivo experiments reveal a more crucial role in tumor growth and metastasis for SNHG1, SNHG3, SNHG5, SNHG12, and SNORA71A." (PMID 36139687, 2022). "HOTAIR and the SNHG12–miR-330-5p–TNC axis might promote tumor progression via tumor cell metastasis and tumor hypoxia." (PMID 35968275, 2022). "We evaluated the expression of RCC1/SNHG3/SNHG12 in 33 different cancer types using several databases such as GEPIA, UALCAN, and TIMER2.0, and found that they were significantly differentially expressed in tumor tissues and normal tissues." (PMID 36148010, 2022). "Finally, SNHG12 was found to act as a sponge for miR-30a-3p, resulting in upregulation of RUNX2, WNT2 and IGF1-1R, contributing to ccRCC tumor progression." (PMID 34884928, 2021). "HuR is a popular tumor-related RBP, and RIP assays were conducted to verify that SNHG12 could bind with HuR." (PMID 33994849, 2021). "The small nucleolar RNA host gene 12 (SNHG12) lncRNA is abnormally expressed in several BC cell lines and this lncRNA’s pro-tumour effect was also found in TNBC tissues where higher expression correlated with tumour size and lymph node metastasis." (PMID 33807045, 2021). "Moreover, overexpression of SNHG12 was also related to clinicopathological characteristics including LNM, distant metastasis, high clinical stage, large tumor size, and poor tumor differentiation in diverse types of cancers." (PMID 33294456, 2020). "SNHG12 expression correlated with the tumor invasion depth (P = 0.021) and TNM stage (P = 0.013), and patients with high SNHG12 expression exhibited poorer overall survival than those with low SNHG12 expression." (PMID 31808752, 2019). "Similarly, two additional studies observed an ~2.3-fold and ~1.3-fold up-regulation of SNHG12 in 22 and 40 NSCLC tumor samples compared to adjacent normal tissues, respectively." (PMID 31620362, 2019). "Similarly, SNHG12 also has a connection with c-Myc as it is a transcriptional target of the oncogene and it is also found upregulated in TNBC where it is correlated with advanced tumor stage and size, and reduced overall survival." (PMID 36139687, 2022).